AGT (angiotensinogen)
Diseases named in the same sentence as AGT in open-access papers (continued):
Sharing a sentence is not in itself a finding about the gene and the disease.
neurological disorders (8 papers, 2017 to 2025). "In accordance with the results obtained in the proteomics study herein reported, an upregulation in Angiotensinogen protein levels was also found in the CSF of patients with secondary progressive MS relative to patients with other neurological disorders." (PMID 35135578, 2022).
adenocarcinoma (1 paper, 2017). A common cancer characterized by the presence of malignant glandular cells. "AGT, which encodes angiotensinogen, the angiotensin peptide precursor, was overexpressed in adenocarcinoma tissue." (PMID 28791183, 2017).
autosomal recessive inherited disorder (1 paper, 2014). "PH1 is a severe autosomal recessive inherited disorder of glyoxylate metabolism caused by mutations in the AGXT gene on chromosome 2q37.3 that encodes the liver-specific PLP-dependent enzyme AGT." (PMID 24934730, 2014).
AGT also shares sentences with these, for which no sentence is quoted: aneurysm (269 papers); abdominal aortic aneurysm (193); aortic aneurysm (192); hypertrophy (90); essential hypertension (78); inflammation (66); Aortic dissection (64); acute respiratory distress syndrome (59); renovascular hypertension (48); Arrhythmia (47); -dependent (38); injury (32); dilatation (26); Hypokalemia (26); malaria (26); pneumonia (25); kidney (23); myocarditis (23); chronic obstructive pulmonary disease (21); glomerular disease (21); Ventricular hypertrophy (21); blood pressure (20); Cerebral ischemia (20); dissection (20); hypertensive heart disease (20); thoracic aortic aneurysm (20); vasculopathy (20); Glomerular sclerosis (19); Hyponatremia (19); Parkinson disease (19).
A further 463 diseases each share a sentence with AGT in 18 papers or fewer.